FGF2 (fibroblast growth factor 2)
Description:
Acts as a ligand for FGFR1, FGFR2, FGFR3 and FGFR4. Also acts as an integrin ligand which is required for FGF2 signaling. Binds to integrin ITGAV:ITGB3. Plays an important role in the regulation of cell survival, cell division, cell differentiation and cell migration. Functions as a potent mitogen in vitro. Can induce angiogenesis. Mediates phosphorylation of ERK1/2 and thereby promotes retinal lens fiber differentiation.
Synonyms: FGF-2; bFGF; HBGF-2; FGFB
Tractability: Small molecule: a structure with a bound ligand is known; a high-quality ligand is known; it has a high-quality binding pocket; it belongs to a druggable protein family. Antibody: UniProt places it where antibodies can reach, with high confidence; its Gene Ontology location is reachable by antibodies, with high confidence. PROTAC: UniProt records ubiquitination sites on it; ubiquitination databases record sites on it; its protein half-life has been measured; a small molecule that binds it is known. Other modalities: a drug acting on it is in phase 2 or 3 trials.
Target class: Secreted protein
Gene: Protein-coding gene on chromosome 4 (122,826,682 to 122,898,236, forward strand). Ensembl gene ENSG00000138685.
Subcellular location: Secreted; Nucleus
Subcellular location (Human Protein Atlas): Nuclear bodies; Nucleoplasm; Predicted to be secreted
Pathways (Reactome):
Signal Transduction: Downstream signaling of activated FGFR1; FGFR1b ligand binding and activation; FGFR1c ligand binding and activation; FGFR2b ligand binding and activation; FGFR2c ligand binding and activation; FGFR3c ligand binding and activation; FGFR4 ligand binding and activation; FGFRL1 modulation of FGFR1 signaling; FRS-mediated FGFR1 signaling; FRS-mediated FGFR2 signaling; FRS-mediated FGFR3 signaling; FRS-mediated FGFR4 signaling; Negative regulation of FGFR1 signaling; Negative regulation of FGFR2 signaling; Negative regulation of FGFR3 signaling; Negative regulation of FGFR4 signaling; PI-3K cascade:FGFR1; PI-3K cascade:FGFR2; PI-3K cascade:FGFR3; PI-3K cascade:FGFR4; PI3K Cascade; PI5P, PP2A and IER3 Regulate PI3K/AKT Signaling; PIP3 activates AKT signaling; Phospholipase C-mediated cascade: FGFR1; Phospholipase C-mediated cascade; FGFR2; Phospholipase C-mediated cascade; FGFR3; Phospholipase C-mediated cascade; FGFR4; RAF/MAP kinase cascade; SHC-mediated cascade:FGFR1; SHC-mediated cascade:FGFR2; SHC-mediated cascade:FGFR3; SHC-mediated cascade:FGFR4; TGFBR3 regulates FGF2 signaling
Disease: Activated point mutants of FGFR2; Constitutive Signaling by Aberrant PI3K in Cancer; Signaling by FGFR1 in disease; Signaling by FGFR2 IIIa TM; Signaling by FGFR2 in disease; Signaling by FGFR3 in disease; Signaling by activated point mutants of FGFR1
and 8 more pathways
Gene Ontology:
Molecular function: chemoattractant activity; chemokine binding; cytokine activity; fibroblast growth factor receptor binding; growth factor activity; identical protein binding; integrin binding; protein binding; receptor-receptor interaction; histone H3K9me2/3 reader activity
Biological process: branching involved in ureteric bud morphogenesis; cell migration involved in sprouting angiogenesis; chondroblast differentiation; fibroblast growth factor receptor signaling pathway; growth factor dependent regulation of skeletal muscle satellite cell proliferation; hyaluronan catabolic process; negative regulation of blood vessel endothelial cell migration; negative regulation of fibroblast migration; negative regulation of wound healing; positive regulation of angiogenesis; positive regulation of blood vessel branching; positive regulation of blood vessel endothelial cell migration; positive regulation of cardiac muscle cell proliferation; positive regulation of cell fate specification; positive regulation of cell migration involved in sprouting angiogenesis; positive regulation of cell population proliferation; positive regulation of DNA biosynthetic process; positive regulation of endothelial cell chemotaxis; positive regulation of endothelial cell chemotaxis to fibroblast growth factor; positive regulation of endothelial cell migration; positive regulation of endothelial cell proliferation; positive regulation of epithelial tube formation; positive regulation of ERK1 and ERK2 cascade; positive regulation of lens fiber cell differentiation; positive regulation of MAP kinase activity; and 37 more
Cellular component: extracellular region; nuclear body; nucleoplasm; nucleus; cytoplasm
Genetic constraint (gnomAD): Loss-of-function variants: 8 observed, 12.4 expected, observed/expected ratio (o/e) 0.65, 90% interval 0.38 to 1.16. The upper end of that interval is the gene's LOEUF score, 1.16, which puts it in group 5 of 6, group 1 being the genes least tolerant of losing a copy. Missense variants: 151 observed, 192.65 expected, observed/expected ratio (o/e) 0.78, 90% interval 0.69 to 0.9. Synonymous variants: 85 observed, 76.37 expected, observed/expected ratio (o/e) 1.11, 90% interval 0.93 to 1.33.
Homologues: Orthologues: chimpanzee FGF2 (100% identical), macaque FGF2 (100% identical), pig FGF2 (99% identical), rabbit FGF2 (99% identical), rat Fgf2 (96% identical), mouse Fgf2 (95% identical), tropical clawed frog fgf2 (83% identical), guinea pig FGF2 (64% identical). Paralogues in human: FGF1 (54% identical), FGF16 (39% identical), FGF5 (38% identical), FGF9 (37% identical), FGF20 (37% identical), FGF3 (36% identical), FGF4 (34% identical), FGF6 (34% identical), FGF7 (33% identical), FGF10 (31% identical), FGF13 (31% identical), FGF14 (31% identical), and 9 more.
Diseases named in the same sentence as FGF2 in open-access papers:
FGF2 is named in the same sentence as 671 diseases in open-access papers, as found by Europe PMC text mining. Sharing a sentence is not in itself a finding about the gene and the disease. The quoted sentences say what the papers report.
breast carcinoma (250 papers, 1994 to 2026). "To validate this discovery in the TCGA ER + breast cancer patients, we analyzed the association between FGF2 and FGFR1 expression and pathway signature scores related to cancer stemness and JAK-STAT pathways." (PMID 38553760, 2024). "This downregulation of VEGF-A/FGF-2 was associated with the inhibition of breast cancer cell migration." (PMID 39184682, 2024). "In preclinical studies, elevated circulating levels of FGF2 have been linked to breast cancer development through the activation of oncogenic signalling pathways, including MAPK/ERK, cMYC and PI3K/AKT/mTOR." (PMID 39251829, 2024). "Another obesity-associated marker of elevated breast cancer risk, especially in the case of visceral fat, is fibroblast growth factor-2 (FGF2), which is released by adipose tissue." (PMID 39251829, 2024). "For example, the upregulation of HS2ST1 was associated with reduced invasive ability by attenuating FGF-2-induced MAPK activation in breast cancer cells." (PMID 39062818, 2024). "There is compelling evidence demonstrating the role of FGF1 and FGF2 as potent angiogenic factors in mediating increased breast cancer risk and progression." (PMID 37800138, 2023). "In our in vitro model of ER+ breast cancer dormancy, FGF-2 induces a complete loss of ER expression in dormant cells, which does not recover upon reawakening." (PMID 37296983, 2023). "Fibroblast growth factors (bFGF/FGF-2) are collectively a family of powerful angiogenic stimulators linked to breast cancer risk." (PMID 32489466, 2020). "Paradoxically, FGF-2 has been demonstrated to inhibit cellular proliferation and promote apoptosis in certain human breast cancer cell lines as well as being associated with good prognostic indicators when over expressed in some breast cancers." (PMID 32012988, 2020). "In FGF-2+ E0771 breast cancers, a significant increase of Iba1+ tumor-associated macrophages (TAMs) was detected by immunostaining." (PMID 32709869, 2020). "It is unlikely that changes in VEGF and FGF2 levels mediate the reduction in risk of post-menopausal breast cancer development in associated with increased levels of exercise." (PMID 31285780, 2019). "Fibroblast growth factor-2 (FGF2) is an interesting candidate in breast cancer pathology as a common single nucleotide polymorphism in the gene has been associated with breast cancer risk in large studies among Western populations." (PMID 31285780, 2019). "Among the affected growth factors, FGF2 has already been reported to be associated with ERK1/2 activation in breast cancer." (PMID 29215790, 2018). "Collectively, these data suggest that the loss of miR-205 induces VEGFA/FGF2 expression, thus conferring chemoresistance in breast cancer." (PMID 27362808, 2016). "The gene is also known to be amplified in squamous cell lung and breast cancer (so is FGF2) and to contain activating mutations in low grade astrocytoma." (PMID 26998479, 2015). "Re-expression of FGF2 in motile MDA MB 231 breast cancer cells results in activation of focal adhesion and loss of motility." (PMID 25629162, 2015). "FGF-2 export and deposition in the endosteal niche appear to be one of the main contributors to the maintenance of dormancy in ER+ breast cancer cells, and the loss of this function in aging MSCs contributes significantly to the observed stochastic recurrence of bone marrow micrometastases." (PMID 37296983, 2023). "The observed discrepancy of FGF2 mRNA expression between the patients’ blood and tissues might be caused by its different functional involvements in breast cancer tissues and blood." (PMID 37445737, 2023). "The HSPGs GPC1 and SDC1, overexpressed in a high percentage of breast cancer pathologies, enhance the mitogen effects associated with heparin-binding growth factors like Basic Fibroblast Growth Factor (FGF2), HBEGF and Hepatocyte growth factor (HGF), promoting cell proliferation." (PMID 33494442, 2021).
breast carcinoma (continued). "Adipose tissue-derived fibroblast growth factor-2 (FGF2) may constitute an additional marker of breast cancer risk, particularly in the context of visceral adiposity." (PMID 33019728, 2020). "Furthermore, the loss of FGF2 re-induced the migration and invasion of breast cancer cells." (PMID 39372951, 2024). "Astrocytic FGF2-mediated paracrine activation of FGFR1 promotes breast cancer brain metastasis in estrogen-treated young mice, but FGF2 levels and signaling decrease in the brain with aging and estrogen-depletion." (PMID 42209519, 2026). "The overexpression of PTX3 in mammary carcinoma cells inhibits FGF2-dependent stimulation of capillary morphogenesis." (PMID 41479916, 2025). "According to the literature, AQP3 seems to be more associated with FGFR-PI3K and FGFR-ERK signaling pathways, being required for FGF-2-induced cell migration in human breast cancer cells and, thus, influencing cancer metastasis." (PMID 40305202, 2025). "Recent studies indicate that PTX3 inhibits FGF2-dependent and FGF8b-induced angiogenesis during breast cancer development." (PMID 41479916, 2025). "Obesity also inhibits the efficacy of anti-VEGF targeted therapy by enhancing the activity of FGF-2 pathway in breast cancer." (PMID 40110127, 2025). "We also show that FGF2 expression in breast cancers coincides with low infiltration of T and B-cells and enriched M2-like macrophage gene signature." (PMID 40425576, 2025). "Clinical studies have shown that the level of FGF2 in the serum of breast cancer patients is significantly elevated." (PMID 41155018, 2025). "We observed that pycnogenol treatment significantly inhibited VEGF-A/FGF-2 gene expression in breast cancer cells." (PMID 39184682, 2024). "YTHDF3 regulates the translation of FGF2 in an m6A-dependent manner, influencing the malignant progression of breast cancer cells." (PMID 39372951, 2024). "Taken together these results suggested a link between FGF2 and Dach1 in influencing stemness/plasticity in breast cancer cells." (PMID 38581619, 2024). "Previous studies have predominantly explored FGF2 as a target within the FGF2/FGFR1 signaling pathway, employing exogenous FGF2 to facilitate breast cancer progression." (PMID 39372951, 2024). "Subsequently, we investigated the mRNA expression of VEGF-A/FGF-2 signaling molecules in breast cancer cells." (PMID 39184682, 2024). "This pre-clinical work lays the foundation for future evaluation of FGF2 as a potential novel therapeutic target for treatment or prevention of breast cancer metastasis to the lung." (PMID 38581619, 2024). "The depletion of FGF2 in breast cancer cell lines notably attenuated their migration, invasion, and clonogenic capacities, while also inducing apoptosis in these cells, echoing findings from a previous study." (PMID 39372951, 2024). "Our analysis of multiple biomolecules revealed that fibroblast growth factor 2 (FGF2) is directly targeted by YTHDF3 in breast cancer cells." (PMID 39372951, 2024). "Breast cancer cells were treated with recombinant mouse (mFGF2) or human (hFGF2) FGF2 protein for 72 h and assessed for changes in stem-like ALDHhiCD44+ phenotype via flow cytometry." (PMID 38581619, 2024). "FGF2 can enhance breast cancer mammosphere regeneration, implying its involvement in fostering cancer stem cells (CSCs), a subpopulation exhibiting stem/progenitor properties with the ability for self-renewal." (PMID 38553760, 2024). "In breast cancer cells, FGF2 exhibits high expression, acting as an anti-apoptotic agent, and induces invasion." (PMID 39091947, 2024). "We next analyzed the associations between FGF2 and FGFR1 gene expression levels and the expression of CDKN1A or CCND1 in the tumor transcriptomes of 601 ER + breast cancer patients from the Cancer Genome Atlas (TCGA)." (PMID 38553760, 2024).
breast carcinoma (continued). "Either autocrine, with high FGF2 expression seen in basal-like breast cancer cell lines, or paracrine, where it is stromal FGF2 that activates hormone receptors and induces proliferation of luminal cancer cells." (PMID 39040443, 2024). "To investigate this, we performed RIP experiments in breast cancer cell lines, which revealed an interaction between FGF2 and YTHDF3 mRNA." (PMID 39372951, 2024). "To test this, we treated breast cancer cells with recombinant FGF2 protein and observed a dose dependent decrease in DACH1 transcript levels as compared to vehicle control (p≤0.05)." (PMID 38581619, 2024). "We studied the effects of FGF2 treatment on proliferation using 3D spheroids of ER + breast cancer cell lines with FGFR1 amplification (CAMA1, MDA-MB-134) and those without (MCF7, T47D)." (PMID 38553760, 2024). "We observed that blocking of FGF2 protein by the neutralizing antibody resulted in significant reduction in growth and colonization of breast cancer cells at days 14 and 21 relative to control (p≤0.05)." (PMID 38581619, 2024). "The results from the analysis of gene expression data from TCGA ER + breast cancer patients using generalized linear models based on also showed a correlation between FGF2, FGFR1 and cell cycle states." (PMID 38553760, 2024). "FGF2 binds to FGFR1 and FGFR2, and at least 10% of breast cancers harbour FGFR1 amplification, which is linked to early relapse and poor prognosis." (PMID 39251829, 2024). "FGF2 secreted by osteogenic cells in the bone microenvironment induces stemness/plasticity in ER+ breast cancer cells by suppressing ER expression." (PMID 38581619, 2024). "The vascular endothelial growth factor-A (VEGF-A) and fibroblast growth factor-2 (FGF-2) signaling pathways play significant roles in breast cancer development and progression." (PMID 39184682, 2024). "To this end, we found that previously identified lung-derived soluble factor FGF2 was important for metastatic colonization of TN breast cancer cells." (PMID 38581619, 2024). "Mechanistically, FRG1 depletion activated the expression of FGF2 in breast cancer cells, which triggered the ERK/AKT cascade in endothelial cells." (PMID 36815234, 2023). "As several studies have reported that FGF2 signalling promotes breast cancer growth, our results pointed to FGF2 signalling as one potential mechanism for CAF‐like support of cancer growth by pleural mesothelial cell populations." (PMID 37691350, 2023). "FGF2 induces breast cancer growth by activating and recruiting ERα and PRBΔ4 isoforms to MYC regulatory sequences." (PMID 37445737, 2023). "Dormant micrometastases that reawaken and undergo MET change their response to FGF-2 by proliferating, in contrast to breast cancer cells expressing an epithelial program." (PMID 37296983, 2023). "An additional study found that circulating FGF2 was directly correlated with BMI in patients with breast cancer, and FGF2 treatment of obese tumor-bearing mice promoted resistance to anti-VEGF therapy." (PMID 37800138, 2023). "Conversely, Api5 knock-down downregulated FGF2 signalling leading to reduced proliferation and diminished in vivo tumorigenic potential of the breast cancer cells." (PMID 37095445, 2023). "In HER2-transformed breast cancer cells, FGF2/FGFR1 were identified to be highly expressed in Lapatinib-resistant populations." (PMID 37800138, 2023). "The graphical representation shows that the depletion of FRG1 in breast cancer cells enhances the level of FGF2." (PMID 36815234, 2023). "The FGF2/FGFR1 paracrine loop is functionally involved in the crosstalk between breast cancer cells and tumor stroma." (PMID 37445737, 2023). "In conclusion, the reduction in FRG1 increases FGF2 expression in breast cancer cells, which activates angiogenic properties of endothelial cells via AKT‐ERK signaling." (PMID 36815234, 2023).